VCP (valosin containing protein)
Description:
Necessary for the fragmentation of Golgi stacks during mitosis and for their reassembly after mitosis. Involved in the formation of the transitional endoplasmic reticulum (tER). The transfer of membranes from the endoplasmic reticulum to the Golgi apparatus occurs via 50-70 nm transition vesicles which derive from part-rough, part-smooth transitional elements of the endoplasmic reticulum (tER). Vesicle budding from the tER is an ATP-dependent process. The ternary complex containing UFD1, VCP and NPLOC4 binds ubiquitinated proteins and is necessary for the export of misfolded proteins from the ER to the cytoplasm, where they are degraded by the proteasome. The NPLOC4-UFD1-VCP complex regulates spindle disassembly at the end of mitosis and is necessary for the formation of a closed nuclear envelope. Regulates E3 ubiquitin-protein ligase activity of RNF19A. Component of the VCP/p97-AMFR/gp78 complex that participates in the final step of the sterol-mediated ubiquitination and endoplasmic reticulum-associated degradation (ERAD) of HMGCR. Mediates the endoplasmic reticulum-associated degradation of CHRNA3 in cortical neurons as part of the STUB1-VCP-UBXN2A complex. Involved in endoplasmic reticulum stress-induced pre-emptive quality control, a mechanism that selectively attenuates the translocation of newly synthesized proteins into the endoplasmic reticulum and reroutes them to the cytosol for proteasomal degradation. Involved in clearance process by mediating G3BP1 extraction from stress granules. Also involved in DNA damage response: recruited to double-strand breaks (DSBs) sites in a RNF8- and RNF168-dependent manner and promotes the recruitment of TP53BP1 at DNA damage sites. Recruited to stalled replication forks by SPRTN: may act by mediating extraction of DNA polymerase eta (POLH) to prevent excessive translesion DNA synthesis and limit the incidence of mutations induced by DNA damage. Together with SPRTN metalloprotease, involved in the repair of covalent DNA-protein cross-links (DPCs) during DNA synthesis. Involved in interstrand cross-link repair in response to replication stress by mediating unloading of the ubiquitinated CMG helicase complex (By similarity). Mediates extraction of PARP1 trapped to chromatin: recognizes and binds ubiquitinated PARP1 and promotes its removal. Required for cytoplasmic retrotranslocation of stressed/damaged mitochondrial outer-membrane proteins and their subsequent proteasomal degradation. Essential for the maturation of ubiquitin-containing autophagosomes and the clearance of ubiquitinated protein by autophagy. Acts as a negative regulator of type I interferon production by interacting with RIGI: interaction takes place when RIGI is ubiquitinated via 'Lys-63'-linked ubiquitin on its CARD domains, leading to recruit RNF125 and promote ubiquitination and degradation of RIGI. May play a role in the ubiquitin-dependent sorting of membrane proteins to lysosomes where they undergo degradation. May more particularly play a role in caveolins sorting in cells. By controlling the steady-state expression of the IGF1R receptor, indirectly regulates the insulin-like growth factor receptor signaling pathway.
Synonyms: IBMPFD; p97; CDC48; TERA; FTDALS6
Tractability: Small molecule: a structure with a bound ligand is known; a high-quality ligand is known; it has a high-quality binding pocket; it belongs to a druggable protein family. Antibody: its Gene Ontology location is reachable by antibodies, with high confidence. PROTAC: UniProt records ubiquitination sites on it; ubiquitination databases record sites on it; its protein half-life has been measured; a small molecule that binds it is known.
Target class: Primary active transporter; Transporter; Endoplasmic reticular retrotranslocon family
Chemical probes: CB-5083 (high quality), CHEMBL1081262, ML080, ML240, ML241, NMS-859, NMS-873
Gene: Protein-coding gene on chromosome 9 (35,053,928 to 35,072,671, reverse strand). Ensembl gene ENSG00000165280.
Subcellular location: Cytoplasm, cytosol; Endoplasmic reticulum; Nucleus; Cytoplasm, Stress granule
Subcellular location (Human Protein Atlas): Cytosol; Nucleoplasm; Basal body; Mitotic spindle; Primary cilium tip; Primary cilium transition zone
Pathways (Reactome):
Metabolism of proteins: E3 ubiquitin ligases ubiquitinate target proteins; Josephin domain DUBs; N-glycan trimming in the ER and Calnexin/Calreticulin cycle; Neddylation; Ovarian tumor domain proteases; Protein methylation; Ribosome Quality Control (RQC) complex extracts and degrades nascent peptide
Disease: Attachment and Entry; Defective CFTR causes cystic fibrosis; Dengue Virus Genome Translation and Replication; Hh mutants are degraded by ERAD
Cellular responses to stimuli: HSF1 activation; KEAP1-NFE2L2 pathway
Immune System: AMPK-induced ERAD and lysosome mediated degradation of PD-L1(CD274); Neutrophil degranulation
Signal Transduction: Hedgehog ligand biogenesis; RHOH GTPase cycle
Autophagy: Aggrephagy
DNA Repair: Translesion Synthesis by POLH
Transport of small molecules: ABC-family protein mediated transport
Gene Ontology:
Molecular function: ATP hydrolysis activity; BAT3 complex binding; deubiquitinase activator activity; identical protein binding; K48-linked polyubiquitin modification-dependent protein binding; polyubiquitin modification-dependent protein binding; protein binding; protein domain specific binding; protein phosphatase binding; RNA binding; ubiquitin protein ligase binding; ubiquitin-like protein ligase binding; ubiquitin-modified protein reader activity; ubiquitin-specific protease binding; ADP binding; ATP binding; hydrolase activity; MHC class I protein binding; protein-containing complex binding
Biological process: autophagosome maturation; autophagy; cellular response to arsenite ion; cellular response to heat; cellular response to misfolded protein; cytoplasm protein quality control; DNA damage response; double-strand break repair; endoplasmic reticulum stress-induced pre-emptive quality control; endosome to lysosome transport via multivesicular body sorting pathway; ERAD pathway; flavin adenine dinucleotide catabolic process; macroautophagy; mitophagy; NAD+ metabolic process; negative regulation of hippo signaling; negative regulation of protein localization to chromatin; negative regulation of smoothened signaling pathway; peptidyl-lysine trimethylation; positive regulation of ATP biosynthetic process; positive regulation of canonical Wnt signaling pathway; positive regulation of mitochondrial membrane potential; positive regulation of non-canonical NF-kappaB signal transduction; positive regulation of oxidative phosphorylation; positive regulation of proteasomal ubiquitin-dependent protein catabolic process; and 28 more
Cellular component: ATPase complex; cytoplasm; cytoplasmic stress granule; cytosol; Derlin-1 retrotranslocation complex; endoplasmic reticulum; endoplasmic reticulum membrane; extracellular exosome; intracellular protein-containing complex; lipid droplet; nucleoplasm; nucleus; perinuclear region of cytoplasm; proteasome complex; protein-containing complex; site of double-strand break; VCP-NPL4-UFD1 AAA ATPase complex; VCP-NSFL1C complex; azurophil granule lumen; extracellular region; ficolin-1-rich granule lumen; intracellular membrane-bounded organelle; RQC complex; secretory granule lumen; cytoplasmic ubiquitin ligase complex; and 3 more
Genetic constraint (gnomAD): Loss-of-function variants: 6 observed, 88.21 expected, observed/expected ratio (o/e) 0.068, 90% interval 0.036 to 0.13. The upper end of that interval is the gene's LOEUF score, 0.13, which puts it in group 1 of 6, group 1 being the genes least tolerant of losing a copy. Missense variants: 353 observed, 1,092.7 expected, observed/expected ratio (o/e) 0.32, 90% interval 0.29 to 0.35. Synonymous variants: 384 observed, 388.42 expected, observed/expected ratio (o/e) 0.99, 90% interval 0.91 to 1.08.
Gene-disease validity (ClinGen):
ClinGen rates the evidence that VCP causes each of these diseases.
inclusion body myopathy with Paget disease of bone and frontotemporal dementia (autosomal dominant): Definitive.
Homologues: Orthologues: chimpanzee VCP (100% identical), guinea pig VCP (100% identical), mouse Vcp (100% identical), rabbit VCP (100% identical), dog VCP (99% identical), rat Vcp (99% identical), macaque VCP (99% identical), tropical clawed frog vcp (98% identical), zebrafish vcp (97% identical), pig VCP (96% identical), Drosophila melanogaster TER94 (83% identical), Caenorhabditis elegans cdc-48.2 (79% identical), and 1 more. Paralogues in human: AFG2A (38% identical), NVL (36% identical), AFG2B (31% identical), PEX1 (28% identical), PEX6 (26% identical).
Diseases named in the same sentence as VCP in open-access papers:
VCP is named in the same sentence as 249 diseases in open-access papers, as found by Europe PMC text mining. Sharing a sentence is not in itself a finding about the gene and the disease. The quoted sentences say what the papers report.
frontotemporal dementia (117 papers, 2008 to 2025). Frontotemporal dementia (FTD) comprises a group of neurodegenerative disorders, characterized by progressive changes in behavior, executive dysfunction and language impairment, as a result of degeneration of the medial prefrontal and frontoinsular cortices. "In those with VCP mutations, cognitive impairment was present in 25.5% of cases, with frontotemporal dementia (FTD) being the most common presentation." (PMID 40649976, 2025). "Accumulation of DNA damage in neuronal stem cell progenitor cells in mice with VCP multisystem proteinopathy mutation was proposed to contribute to the early stages of Frontotemporal dementia (FTD) pathology." (PMID 38701207, 2024). "Multisystem proteinopathy 1 (MSP1), also known as IBMPFD (inclusion body myopathy associated with Paget’s disease of bone and frontotemporal dementia), or VCP-disease has been associated with more than 100 heterozygous missense pathogenic variants in VCP." (PMID 38891822, 2024). "Mutation D395G in VCP causes vacuolar tauopathy, a type of frontotemporal dementia with widely distributed and abundant filamentous tau inclusions." (PMID 38758288, 2024). "VCP mutations are associated with various degenerative conditions, including frontotemporal dementia (FTD), inclusion body myopathy (IBM), Paget’s disease, amyotrophic lateral sclerosis, and Charcot-Marie-Tooth disease." (PMID 38145206, 2024). "Pathological VCP variants can trigger inclusion body myopathy associated with Paget disease of the bone and frontotemporal dementia (IBMPFD); this rare disease is also described by the more general term multisystem proteinopathy (MSP)." (PMID 37545006, 2023). "Multisystem proteinopathy 1, or inclusion body myopathy associated with Paget’s disease of bone and frontotemporal dementia, is a rare autosomal dominant disease caused by mutations in the VCP gene." (PMID 36980948, 2023). "Mutations in p97/VCP cause two motor neuron diseases: inclusion body myopathy associated with Paget disease of bone and frontotemporal dementia and familial amyotrophic lateral sclerosis." (PMID 35865348, 2022). "Mutations in VCP were identified as the cause of inclusion body myopathy with Paget disease of bone and frontotemporal dementia (IBMPF);." (PMID 36570531, 2022). "Multisystem proteinopathy caused by variants in the VCP gene is characterized by inclusion body myopathy, Paget disease of the bone, and frontotemporal dementia." (PMID 34998409, 2022). "Inversion in the VCP gene was associated with bulbar onset (p = 3.5 × 10−12) and frontotemporal dementia (p = 1.1 × 10−4)." (PMID 35091648, 2022). "VCP mutations are associated with human diseases, such as multisystem disease inclusion body myopathy associated with Paget’s disease and frontotemporal dementia (IBMPFD), amyotropic lateral sclerosis, and Parkinson’s disease (27, –, 29)." (PMID 35089078, 2022). "Heterozygous germline mutations in VCP have been previously associated with Paget disease of bone and frontotemporal dementia, amyotrophic lateral sclerosis (ALS) and type 2 Charcot–Marie–Tooth disease." (PMID 35273242, 2022). "For example, mutations in VCP have also been identified in other neurodegenerative diseases, including Inclusion Body Myopathy, Paget’s disease and Frontotemporal Dementia (IBMPFD)." (PMID 34396115, 2021). "Inclusion body myopathy (IBM) with Paget’s disease of bone (PDB) and/or frontotemporal dementia (FTD) (IBMPFD) was recently identified as rare autosomal dominant disorder due to mutations in VCP gene." (PMID 34917136, 2021). "Dilated cardiomyopathy is observed in patients with IBMPFD (inclusion body myopathy (IBM), Paget disease (PDB), neurological components frontotemporal dementia (FTD)) who experience pain due to VCP/p97 mutations." (PMID 33439255, 2021).
frontotemporal dementia (continued). "Inclusion body myopathy with early-onset Paget disease and fronto-temporal dementia (FTD) is a rare hereditary disease caused by mutations mostly in the valosin containing protein (VCP) gene, with an autosomal dominant pattern of inheritance." (PMID 32471196, 2020). "Mutations in Valosin containing protein (VCP) was initially discovered as the cause of a clinical syndrome characterized by the triad of inclusion body myopathy, Paget’s disease of bone, and frontotemporal dementia (IBMFTD) in 2004." (PMID 32116499, 2020). "Dominantly inherited VCP mutations cause inclusion body myopathy with Paget disease of bone and frontotemporal dementia." (PMID 31370276, 2019). "Mutations of the VCP (also known as p97) gene have been identified in patients with frontotemporal dementia, amyotrophic lateral sclerosis (ALS), autism spectrum disorders (ASD) and hereditary spastic paraplegia (HSP)." (PMID 29310658, 2018). "VCP mutations were first associated with inclusion body myopathy with Paget's disease of bone and frontotemporal dementia (IBMPFD) but was later associated with amyotrophic lateral sclerosis and Charcot-Marie-Tooth disease." (PMID 29899994, 2018). "Mutations in the gene encoding valosin-containing protein (VCP) lead to multisystem proteinopathies including frontotemporal dementia." (PMID 28360103, 2017). "Mutations in VCP have been found in patients with inclusion body myopathy with early-onset Paget disease and frontotemporal dementia as well as familial amyotrophic lateral sclerosis (ALS)." (PMID 28360103, 2017). "A VCP mutation linked to inclusion body myopathy with Paget's disease of the bone and frontotemporal dementia (IBMPFD) impairs ER-associated degradation of ubiquitinated proteins from the ER22." (PMID 27080313, 2016). "Mutations in VCP have been linked to severe degenerative disorders including inclusion body myopathy with frontotemporal dementia (IBMPFD) and amyotrophic lateral sclerosis." (PMID 26544960, 2015). "Mutations in the VCP gene have previously been identified in families with inclusion body myopathy, Paget disease, and frontotemporal dementia (IBMPFD)." (PMID 26213621, 2015). "Mutations in the VCP gene were first found to cause inclusion-body myopathy with early-onset Paget disease and frontotemporal dementia (IBMPFD)." (PMID 25492614, 2014). "The importance of VCP for autophagy is confirmed by the inclusion body/familial VCP myopathy associated with frontotemporal dementia and Paget's disease of bone, caused by mutations in VCP." (PMID 25028670, 2014). "VCP mutations are the cause of inclusion body myopathy, Paget’s disease of the bone, and frontotemporal dementia (IBMPFD) and they account for 1%–2% of familial amyotrophic lateral sclerosis (ALS)." (PMID 23498975, 2013). "Some autosomal dominant mutations in the VCP gene cause inclusion body myopathy with Paget disease of the bone and frontotemporal dementia (IBMPFD) which is a rare, late age–onset inherited degenerative disorder that can affect the muscles, bones and brain." (PMID 22870330, 2012). "Pathogenic mutations in VCP/p97 cause disorders including frontotemporal dementia, amyotrophic lateral sclerosis, and Parkinsonism; in addition to promoting lysophagy, VCP/p97 is also an effector of macroautophagy, and both of these functions likely contribute to neuron pathologies." (PMID 41439996, 2025). "Besides mutation D395G, other mutations in VCP cause multisystem proteinopathy, a degenerative disease affecting muscle and bone, that can also present as frontotemporal dementia with TDP-43 inclusions." (PMID 38758288, 2024). "However, 2 to 3% of the patients who carry pathogenic VCP mutations show only frontotemporal dementia." (PMID 37545006, 2023).